ALKBH5 (alkB homolog 5, RNA demethylase)
Diseases named in the same sentence as ALKBH5 in open-access papers (continued):
Sharing a sentence is not in itself a finding about the gene and the disease.
lung carcinoma (continued). "We conclude that loss of LKB1 promotes ALKBH5 transcription by a DNA methylation mechanism, reduces m6A modification, and increases the stability of m6A target oncogenes, thus contributing to aggressive phenotypes of KRAS-mutated lung cancer." (PMID 34016959, 2021). "ALKBH5 gain- or loss-of function could effectively reverse LKB1 regulated cell proliferation, colony formation, and migration of KRAS-mutated lung cancer cells." (PMID 34016959, 2021). "Moreover, knockdown of ALKBH5 inhibited the angiogenesis of lung cancer in vitro and in vivo." (PMID 36376862, 2022). "Furthermore, the expression and stability of lncRNA PVT1 (long noncoding RNA plasmacytoma variant translocation 1) were regulated by ALKBH5, and PVT1 overexpression partially restored the proliferation, migration and angiogenesis of lung cancer cells, which was suppressed by ALKBH5 knockdown." (PMID 36376862, 2022). "Furthermore, we found that ALKBH5 promotes angiogenesis in lung cancer." (PMID 36376862, 2022). "In addition, ALKBH5 can inhibit the miR-107-LATS2 signaling axis, reduce the activity of YAP and inhibit the growth and metastasis of tumor cells, which may be a potential strategy for the treatment of lung cancer by targeting ALKBH5." (PMID 35022030, 2022). "Additionally, recent papers have shown that ALKBH5 plays diverse roles in lung cancer." (PMID 35628623, 2022). "Thus, our clinical data further confirmed that LKB1 loss increased the DNA methylation and expression level of ALKBH5, which resulting in the demethylation of m6A modification on SOX2, SMAD7, and MYC, and maintaining their expression for KRAS mutant lung cancer." (PMID 34016959, 2021). "Moreover, effective inhibition of m6A modification of ALKBH5 might constitute a potential treatment strategy for lung cancer." (PMID 32106857, 2020). "In lung cancer tissues, elevated expression of FTO and ALKBH5 promotes tumor cell proliferation, with m6A modifications playing a crucial role." (PMID 40916616, 2025). "To investigate the role of RNA demethylases in the regulation of cell differentiation in lung cancer, we depleted the two known m6A RNA demethylases, FTO and ALKBH5, in two different human LUAD cell lines: A549 and H358." (PMID 41301413, 2025). "Our results revealed low expression levels of both ALKBH5 and FTO in lung cancer tissues, with ALKBH5 being the sole enzyme showing negative regulation of HMMR." (PMID 39990663, 2025). "Consistently, ALKBH5 PTMs, including phosphorylation and SUMOylation, are much more abundant in KRAS-mutant primary lung cancer cells compared with KRAS WT cells." (PMID 39960727, 2025). "lncRNA PVT1 promoted vascular generation in lung cancer tissue, and ALKBH5 reduced m6A modification on PVT1, thereby facilitating vascular generation in lung cancer." (PMID 39220683, 2024). "Like ALKBH5, FTO is downregulated as a tumor suppressor in a variety of cancers, including BC, lung cancer, CRC, bladder cancer, prostate cancer, ccRCC, and adrenocortical cancer." (PMID 37007161, 2023). "Our results demonstrate that ALKBH5 contributes to proliferation, migration and angiogenesis through PVT1 in lung cancer, thus providing a potential antitumor therapeutic target for lung cancer patients." (PMID 36376862, 2022). "A public database was used to analyze the expression and overall survival of ALKBH5 and PVT1 in lung cancer patients." (PMID 36376862, 2022). "Several studies on lung cancer have shown that FTO plays a cancer-promoting role through m6A modification in lung squamous cell carcinoma and adenocarcinoma, whereas ALKBH5 inhibits NSCLC tumorigenesis by reducing YTHDFs-mediated YAP expression." (PMID 35318440, 2022). "Our study reveals that ALKBH5 promotes lung cancer progression and angiogenesis through PVT1, suggesting novel therapeutic targets for lung cancer patients." (PMID 36376862, 2022).
lung carcinoma (continued). "Tube formation assay also showed that the tube formation ability, which was suppressed by silencing ALKBH5, was partially rescued by PVT1 overexpression in lung cancer cells." (PMID 36376862, 2022). "ALKBH5 and FTO expression were evaluated in immortalized bronchial epithelial cells (BEAS2B) and lung cancer cell lines." (PMID 35318440, 2022). "Mechanistic studies showed that knockdown of ALKBH5 decreased the expression and stability of PVT1 in lung cancer cells." (PMID 36376862, 2022). "In a previous study, knockdown of ALKBH5 and PVT1 in lung cancer cells inhibited tumor growth in mouse models." (PMID 36376862, 2022). "Mechanistically, our results showed that ALKBH5 regulates the expression and RNA stability of PVT1 in lung cancer." (PMID 36376862, 2022). "We then detected the expression of ALKBH5 in four lung cancer cell lines (A549, H1299, H1975, PC9) and human bronchial epithelial cell line (16HBE), and found that ALKBH5 was more highly expressed in H1975 and A549 cells than in 16HBE cells." (PMID 36376862, 2022). "Here, our data indicate that ALKBH5 increased the expression of PVT1 by enhancing its stability and that ALKBH5 can regulate the proliferation, migration and angiogenesis of lung cancer partially through PVT1 in lung cancer cells." (PMID 36376862, 2022). "ALKBH5 protein expression was negatively correlated with m6A level, in contrast to positive correlation with the tumor size, TNM and clinical stage in K lung cancer patients." (PMID 34016959, 2021). "To investigate how m6A is regulated in KL lung cancer, we compared the expression of proteins that act as the m6A writer complex (METTL3, METTL14, and WTAP) and erasers (ALKBH5 and FTO)." (PMID 34016959, 2021). "The results showed that the expression profiles of eight m6A regulators (ALKBH5, FTO, HNRNPC, METTL14, RBM15, YTHDC1, YTHDC2, and ZC3H13) were significantly different among the three different lung cancer subtypes (P < 0.01)." (PMID 34805165, 2021). "We also tested the expression of m6A writers METTL3, METTL14, and WTAP and of erasers ALKBH5 and FTO after the treatment of IL-37 in A549 cells and lung cancer tissues." (PMID 33489865, 2020). "We also showed the expression of m6A writers METTL3, METTL14, and WTAP and erasers ALKBH5 and FTO in A549 cells and lung cancer tissues after the treatment of IL-37." (PMID 33489865, 2020). "Our results demonstrate that ALKBH5 promotes the progression and angiogenesis of lung cancer by regulating the expression and stability of PVT1, which provides a potential prognostic and therapeutic target for lung cancer patients." (PMID 36376862, 2022). "Additionally, we evaluated the expression of ALKBH5 target mRNAs CDKN1A and TIMP3 in lung cancer using the TCGA dataset." (PMID 35318440, 2022). "Furthermore, we identified that the mechanism by which ALKBH5 regulates proliferation, migration and angiogenesis includes the regulation of the stability of PVT1 in lung cancer cells." (PMID 36376862, 2022). "Due to the importance of VEGFA in angiogenesis, we first analyzed the correlation of expression between ALKBH5 and VEGFA in lung cancer tissues using the GEPIA website and found that the expression levels of ALKBH5 were positively correlated with VEGFA in lung cancer tissues." (PMID 36376862, 2022). "Furthermore, m6A regulators play an important role in lung cancer progression, for example FTOH and ALKBH5 have been shown to promote the proliferation of lung cancer cells, and YTHDF2 can regulate tumor metabolism." (PMID 34805165, 2021). "Some research found that ALKBH5 knockout resulted in spermatogenesis defects due to elevated spermatocyte apoptosis; disruption of the transcription process by METTL3 and METTL14 could lead to lung fibrosis and lung cancer metastasis." (PMID 38133427, 2023). "Furthermore, the knockdown of FTO did not suppress the proliferation of lung cancer cells, but the knockdown of ALKBH5 inhibited it." (PMID 35318440, 2022).
lung carcinoma (continued). "Our results showed that silencing ALKBH5 and PVT1 suppressed the proliferation of lung cancer cells in zebrafish xenografts, which is consistent with the results of mouse models, indicating that zebrafish xenografts could be a reliable model for human cancer research." (PMID 36376862, 2022). "Finally, we investigated the functional mechanism between ALKBH5 and PVT1 in lung cancer cells." (PMID 36376862, 2022). "As lung cancer tissues with high ALKBH5 expression also showed high macrophage infiltration, we explored the mechanism by which ALKBH5 recruits macrophages to infiltrate the TME by performing RNA sequencing of NSCLC cells with or without ALKBH5 knockdown." (PMID 38872221, 2024). "However, a mouse model for studying the metastatic roles of ALKBH5 and PVT1 in lung cancer is lacking." (PMID 36376862, 2022).
colorectal cancer (41 papers, 2020 to 2025). A primary or metastatic malignant neoplasm that affects the colon or rectum. "M6A was positively associated with RP11–138 J23.1 (RP11) expression when ALKBH5 was overexpressed in colorectal cancer." (PMID 31931709, 2020). "The role of RNA N6-methyladenoine (m6A) eraser AlkB homologue 5 (ALKBH5) in colorectal cancer (CRC) stem cells (CSCs) is unclear." (PMID 41390849, 2025). "Increasing m6A levels via m6A demethylase Alkbh5 knockout suppressed the tumour‐promoting effects of colorectal cancer EVs." (PMID 40326665, 2025). "Relevant studies have demonstrated the efficient in vivo delivery of ALKBH5 mRNA to colorectal cancer cells using folic acid‐modified EVs‐liposome hybrid nanoparticles (FA‐ELNPs), significantly inhibiting the progression of colorectal cancer." (PMID 41476648, 2025). "Specifically, in colorectal cancer, ALKBH5 exhibits an immunosuppressive activity by targeting AXIN2." (PMID 40746892, 2025). "In MDSCs from colorectal cancer models, ALKBH5 downregulation elevated m6A and arginase-1 expression; whereas restoring ALKBH5 curtailed MDSC suppressive activity and protumor effects in vivo." (PMID 41280938, 2025). "In preclinical tumor models, an ALKBH5 mRNA delivery system restored ALKBH5 levels at the tumor site, suppressing colorectal cancer growth and offering a novel clinical target." (PMID 38856795, 2024). "CARMN was identified as a major regulator in colorectal cancer, directly demethylated by ALKBH5, thereby acting as a suppressive modulator of colorectal cancer proliferation and differentiation." (PMID 39039912, 2024). "Chen Rui's team detected a significant downregulation of ALKBH5 in 1,078 patients with colorectal cancer tissues compared to healthy controls in a ten-year follow-up cohort and the TCGA dataset." (PMID 38856795, 2024). "Whereas in CRC, despite little ALKBH5 expression, studies have found that external introduction of high levels of ALKBH5 can effectively suppress colorectal cancer progression by inhibiting glycolysis." (PMID 38711100, 2024). "In colorectal cancer under high-fat conditions, ALKBH5 and FTO downregulation increases m6A methylation on HK2 mRNA through IGF2BP2." (PMID 38856795, 2024). "Considering that AlkB homolog 5 (ALKBH5) is a well‐described m6A demethylase in previous enzyme assays, we aimed to investigate the role of m6A methylation alteration conferred by disturbed ALKBH5 in colorectal cancer (CRC) development." (PMID 37203239, 2023). "Similarity, a similar study in colorectal cancer has also demonstrated the positive connection between ALKBH5 and FABP5." (PMID 37858219, 2023). "One study found that ALKBH5 can affect the tumor microenvironment of colorectal cancer, thus mediating the resistance of colorectal cancer patients to the anti-PD-1 therapy response." (PMID 35614935, 2022). "ALKBH5 knockdown suppresses the proliferative and migratory abilities of colorectal cancer cells partially through ALKBH5-related NEAT1 downregulation, which is consistent with the finding in GC cells." (PMID 35063010, 2022).
colorectal cancer (continued). "Meanwhile, ALKBH5 inhibitors can significantly improve immunotherapy efficacy, providing new possibilities for targeted therapy of colorectal cancer, melanoma, and other malignant tumors." (PMID 35614935, 2022). "Together, these demonstrated that ALKBH5 can not only be used as a breakthrough target for the clinical treatment of colorectal cancer in the future, but also has the potential to become a new biomarker for the patient population." (PMID 35614935, 2022). "Preliminary progress has also been made in the mechanism study of another demethylase, ALKBH5, in mediating colorectal cancer metastasis and immunotherapy resistance." (PMID 35614935, 2022). "ALKBH5 also reduced γH2AX formation after X-ray irradiation in HCT116 colorectal cancer cells." (PMID 40341728, 2025). "Focusing on the eraser ALKBH5, several experimental systems indicate that m6A demethylation promotes immunosuppressive myeloid states: in colorectal cancer, ALKBH5 upregulated CPT1A and drove M2 polarization, facilitating tumor progression; genetic or pharmacologic interference reduced M2 programs." (PMID 41280938, 2025). "Researchers have successfully synthesized folate-modified exosome-liposome hybrid nanoparticles loaded with ALKBH5 mRNA, which showed significant inhibition of colorectal cancer progression in tumor models by modulating the ALKBH5/JMJD8/PKM2 axis and hampering glycolysis." (PMID 38965553, 2024). "Furthermore, LKB1 expression negatively correlated with ALKBH5 expression was also found in KRAS-mutated pancreatic and colorectal cancer cell lines." (PMID 34016959, 2021). "The research results show that m6A demethylase in tumor cells contributes to the effect of immunotherapy, and ALKBH5 is identified as a potential therapeutic target to improve the efficacy of immunotherapy for melanoma, colorectal cancer and other potential cancers." (PMID 35069586, 2021). "Moreover, downregulation of ALKBH5 is correlated with poor prognosis in colorectal cancer patients." (PMID 38856795, 2024). "However, the role and mechanisms of ALKBH5 in colorectal cancer (CRC) is unclear." (PMID 35979628, 2022). "However, ALKBH5 in colorectal cancer plays an anti-cancer effect." (PMID 33237039, 2020). "Similar to other tumors, the regulation of m6A modifications in colorectal cancer is equally diverse and complex, and almost all m6A modifiers except METTL14, ZC3H13, METTL3, FTO, ALKBH5, and YTHDF2 promote colorectal carcinogenesis." (PMID 39967906, 2025). "Here the authors show that the RNA N6-methyladenoine (m6A) eraser ALKBH5 destabilizes FAM84A mRNA to prevent β-catenin ubiquitination and degradation, contributing to colorectal cancer stemness and chemoresistance." (PMID 41390849, 2025). "For instance, in colorectal cancer, overexpression of FTO and ALKBH5 suppresses proliferation both in vitro and in vivo, whereas their silencing enhances tumor growth." (PMID 41141648, 2025). "ALKBH5 reduces the transcriptional level of SLC7A11 by deleting m6A modification, thereby promoting ferroptosis in colorectal cancer." (PMID 39248438, 2024). "They found the upregulation of more m6A‐associated genes in tumour tissues than in normal tissues, as well as the downregulation of ALKBH5, YTHDF3 and METTL14 in colorectal cancer (CRC)." (PMID 34647424, 2022). "However, all analyzed ALKBH5 SNPs (rs2124370, rs8400, rs9899249, rs9913266, and rs2925137) could not predispose to colorectal cancer." (PMID 33790968, 2021).
colorectal cancer (continued). "Specifically, ALKBH5 gene DNA methylation positively correlated with ALKBH5 mRNA expression in KRAS mutant lung, and colorectal cancer cell lines, based on the CLLE database." (PMID 34016959, 2021). "Moreover, in a high-fat environment, downregulated FTO and ALKBH5 cooperatively activated FOXO signaling through IGF2BP2-mediated m6A methylation in HK2 mRNA, which boosted glycolysis in colorectal cancer." (PMID 40001461, 2025). "Besides, ALKBH5, FTO, METTL3, METTL14, METTL16 and WTAP were detected in a section of colorectal cancer tissue." (PMID 39039912, 2024). "Besides being a well-known m6A writer, ALKBH5 also collaborates with METTL14/IGF2BPs to suppress tumor cell glycolysis by negatively regulating the JMJD8/PKM2 signaling axis, thereby slowing down colorectal cancer progression." (PMID 38856795, 2024). "Molecular investigations indicate that ALKBH5 collaborates with METTL14/IGF2BPs to suppress tumor cell glycolysis by negatively regulating the Jumonji domain-containing protein 8 (JMJD8)/pyruvate kinase M2 (PKM2) signaling axis, slowing down colorectal cancer progression." (PMID 38856795, 2024). "Therefore, it can be speculated that ALKBH5, METTL3, and FTO may accelerate the growth of colorectal cancer." (PMID 37511932, 2023).